IFNGR1 (interferon gamma receptor 1)
Diseases named in the same sentence as IFNGR1 in open-access papers (continued):
Sharing a sentence is not in itself a finding about the gene and the disease.
E. coli infection (1 paper, 2020). "The E. coli infection of IPEC-1 cells induced the upregulation of the IFNB1 gene encoding interferon beta 1 (logFC of 3.63) and the IFNGR1 gene (logFC of 3.55), encoding the ligand-binding alpha chain of the gamma interferon receptor." (PMID 32234079, 2020).
Ewing sarcoma (1 paper, 2023). A small round cell tumor that lacks morphologic, immunohistochemical, and electron microscopic evidence of neuroectodermal differentiation. "Synergistic induction of CXCL9/CXCL10 was completely ablated by IFNGR1 depletion, and partly inhibited by IFNAR1 depletion, indicating that Ewing sarcoma–intrinsic signaling through both pathways contributes to this feedforward loop." (PMID 37615015, 2023).
fibrosarcoma (1 paper, 2022). A malignant mesenchymal fibroblastic neoplasm affecting the soft tissue and bone. "Our study corroborates an early pioneering study by Bob Schreiber and colleagues, which demonstrated that IFNγR1 truncation in methA fibrosarcoma decreased tumor immunogenicity and responsiveness to LPS therapy." (PMID 36008408, 2022).
fibrosis (1 paper, 2023). the formation of excess fibrous connective tissue in an organ or tissue in a reparative or reactive process. "Furthermore, increased IL1RL1 and decreased IFNGR1 expressions are confirmed in ILC2s from individuals with idiopathic PF, highlighting the applicability of Ifngr1-/-Rag2-/- mice as a mouse model for fibrosis research." (PMID 38097562, 2023).
Giardia infections (1 paper, 2022). "Several cytokine receptors are differentially expressed during the Giardia infections, including IL11RA, IFNGR1, IFNGR2, IL10RA, and ACKR3." (PMID 35573800, 2022).
Granuloma (1 paper, 2008). A compact, organized collection of mature mononuclear phagocytes, which may be but is not necessarily accompanied by accessory features such as necrosis. "By day 90 post-infection, Ifngr1−/− mice presented massive mycobacterial dissemination associated with large necrotising granulomas." (PMID 18232731, 2008). "Histological observations confirmed dissemination in the Ifngr1−/− cohort, contrasting with small, well-delimited granulomas in Ifngr1+/+ animals (unpublished data)." (PMID 18232731, 2008). "Two weeks after infection, Ifngr1−/− mice had fewer and smaller granulomas in both the spleen and the liver than infected Ifngr1+/+ control mice." (PMID 18232731, 2008). "In contrast, a very small number of small, well-delimited granulomas were observed in infected Ifngr1+/+ control mice (unpublished data)." (PMID 18232731, 2008). "Granulomas were mostly lymphoid, with no recruitment of epithelioid cells, whereas the granulomas observed in Ifngr1+/+ BCG-infected mice contained mostly epithelioid cells and a few lymphocytes (unpublished data)." (PMID 18232731, 2008).
Graves disease (1 paper, 2014). Graves' disease is an autoimmune disorder that leads to overactivity of the thyroid gland (hyperthyroidism).It is caused by an abnormal immune system response that causes the thyroid gland to produce too much thyroid hormones. "Genotypic frequencies and association given by the odds ratio (OR) and 95% confidence intervals (95% CI) between genetic variants in IL1B, TNFA, IL6, and IFNGR1, and Graves' disease and Hashimoto's thyroiditis." (PMID 25127106, 2014). "Polymorphisms in the IL6-174 G/C (rs1800795), TNFA-308 G/A (rs1800629), IL1B-511 C/T (rs16944), and IFNGR1-56 T/C (rs2234711) genes were assessed in a case-control study comprising 420 Hashimoto's thyroiditis patients, 111 Graves' disease patients and 735 unrelated controls from Portugal." (PMID 25127106, 2014).
head and neck squamous cell carcinoma (1 paper, 2024). A squamous cell carcinoma that arises from any of the following anatomic sites: lip and oral cavity, nasal cavity, paranasal sinuses, pharynx, larynx, and salivary glands. "EVs from head and neck squamous cell carcinoma cells transport phosphorylated interferon gamma receptor 1 (IFNGR1) to fibroblastic reticular cells within sentinel lymph nodes, activating the JAK/STAT1 pathway without binding to IFNG, thereby promoting PD-L1 transcription." (PMID 39528800, 2024).
Hepatic fibrosis (1 paper, 2015). The presence of excessive fibrous connective tissue in the liver. "Severe hepatic fibrosis due to S. mansoni infection was also associated with variation at 6q22-23, close to the gene for the IFNγ receptor α chain (IFNGR1)." (PMID 26540410, 2015). "Studies in a Sudanese population indicated that a major codominant locus controlling hepatic fibrosis in schistosomiasis was at 6q22-q23, close to the gene for the IFNGR1 chain." (PMID 26540410, 2015).
intestinal infection (1 paper, 2024). "Next, to determine whether the systemic spread of CR6 required initial intestinal infection for subsequent dissemination or could occur independent of the intestine, we analyzed the distribution of barcodes across tissues in WT, Ifnar1-/-, Ifnar1-/-Ifngr1-/-, and Stat1-/- mice." (PMID 38701091, 2024).
intestinal tumors (1 paper, 2016). "Furthermore, the Ifngr1 was significantly downregulated in intestinal tumors when compared to mucosa." (PMID 27286456, 2016). "Correspondingly, Ifngr1 is downregulated in intestinal tumors from Ifngr1+/+ApcMin/+ mice." (PMID 27286456, 2016).
lung disease (1 paper, 2022). "Although it has been suggested that IFNAR1 mediates STING-associated autoinflammation, we discovered an unexpected role for IFNGR1 in regulating lung disease and T cell and macrophage dysfunction in SAVI mice that have a STING gain-of-function mutation." (PMID 36073546, 2022). "We observed that deletion of Ifngr1 protects against autoinflammatory lung disease." (PMID 36073546, 2022). "Future studies involving the cell type–specific deletion of Ifngr1 will determine in which cells IFNGR1 expression is necessary and sufficient to regulate lymph node development, lung disease, and T cell survival in SAVI mice." (PMID 36073546, 2022). "Our discoveries indicate that STING-associated lung disease and T cell phenotypes are indeed IFN related but unexpectedly mediated by IFNGR1, rather than by IFNAR1 or IFNλR1." (PMID 36073546, 2022). "Because T cells play a major role in lung disease in SAVI mice, we reasoned that IFNGR1 may also have direct effects on T cells." (PMID 36073546, 2022).
lung fibrosis (1 paper, 2024). "Inactivation of interferon receptor 1 (Ifngr1) reduced dysplastic cell formation, ameliorated lung fibrosis, and improved lung-function recovery." (PMID 39352385, 2024).
neuroblastoma (1 paper, 2022). Neuroblastoma (NB) is the most common solid, extracranial childhood tumor. "To investigate whether human cell type affects IFNGR1 mRNA accessibility, we re-screened the compounds in human neuroblastoma SH-SY5Y cells." (PMID 35477658, 2022).
ovarian tumor (1 paper, 2018). "In fact, elegant murine models demonstrate that IFNGR1-/- mice exhibit more rapid ovarian tumor progression and the reduction in IFNGR has been proposed as a mechanism for evading tumor surveillance." (PMID 29474442, 2018).
pneumococcal pneumonia (1 paper, 2022). A febrile disease caused by STREPTOCOCCUS PNEUMONIAE. "To test whether the essential role for IFN-γ in remodeling AM after pneumococcal pneumonia required IFN-γ signaling to AM, we crossed Ifngr1-floxed mice with Itgax-driven Cre transgenic mice to delete IFN-γ receptors from CD11c+ cells." (PMID 35133985, 2022).
portal hypertension (1 paper, 2021). Increased blood pressure in the portal venous system. "Further analysis showed that a co-dominant gene called SM2, located in the 6q22-q23 region, close to the interferon-gamma receptor 1 (IFNGR1) gene, which encodes the IFN-γ α chain receptor and controls disease progression by affecting fibrosis and portal hypertension." (PMID 34281269, 2021).
preeclampsia (1 paper, 2025). Preeclampsia is a hypertensive disorder of pregnancy that is characterized by new-onset hypertension with proteinuria presenting after 20 weeks of gestation, and depending on mild or severe forms may initially present with severe headache, visual disturbances, and hyperreflexia. "IFNγR1 polymorphisms contribute to preeclampsia pathophysiology and the amount of IFNγR1+ monocytes and the intensity of IFNγR1-expression were increased in preeclampsia." (PMID 40698658, 2025).
prion disease (1 paper, 2020). A transmissible disease that is caused by a protein that is able to induce abnormal folding of normal cellular proteins, leading to characteristic spongiform brain changes, which are associated with neuronal loss without an inflammatory response. "This cytokine can similarly stimulate neurotoxic reactive astrocyte activation, and IFNGR1 expression is upregulated in reactive astrocytes during CNS prion disease, in aging human brains and patients with Parkinson’s disease and Alzheimer’s disease." (PMID 33023255, 2020). "However, since IFN-γ is not induced in mice infected with prions alone in the steady state, the induction of IFNGR1 in the reactive astrocytes in response to CNS prion disease most likely primes them to respond to subsequent IFN-γ-mediated stimulation." (PMID 33023255, 2020).
scrub typhus (1 paper, 2024). Scrub typhus is a rare dust mite-borne infectious disease caused by the Orientia tsutsugamushi bacterium and characterized clinically by an eruptive fever which is potentially serious. "As Ifngr1-/- mice were highly susceptible to Ot infection, this mouse model may hold promise for investigating severe scrub typhus pathogenesis, bacterial virulence factors, and host immunity." (PMID 38743761, 2024). "Using double Ifnar1-/-Ifngr1-/- and Stat1-/- mice, we found that deficiency in IFN/STAT1 signaling resulted in lethal infection with profound pathology and skin eschar lesions, which resembled to human scrub typhus." (PMID 38743761, 2024). "In contrast, both double Ifnar1-/-Ifngr1-/- and Stat1-/- mice displayed evident skin lesions marked by necrosis of the overlying epidermis and hardening features, surrounded by an indurated red halo (red arrows), which resembled skin eschars in scrub typhus patients." (PMID 38743761, 2024). "Eschar formation in Ifngr1-/- mice highlights the important role of the IFN-γ signal in controlling skin lesions, suggesting that IFN-γ levels and its downstream JAK/STAT signals as key determinants of human scrub typhus." (PMID 38743761, 2024).
systemic sclerosis (1 paper, 2024). A chronic disorder, possibly autoimmune, marked by excessive production of collagen which results in hardening and thickening of body tissues. "The polymorphisms identified in ACE2 (chrX_15596143), IL-18 (chr11_112014152), IL-18R1 (chr2_103013408), IFNGR1 (chr6_137519588), and IL-2 (chr4_123377482) genes can be considered predisposing factors for the onset of systemic sclerosis." (PMID 38675400, 2024).
vasculitis (1 paper, 2021). "In Ifnar1-/-;Ifngr1-/- mice, we observed necrosis, vasculitis, fibrin thrombi, and rickettsial staining that coincided primarily with infiltrating macrophages and neutrophils." (PMID 34423779, 2021).
tumor (150 papers, 2009 to 2026). "S12), which consistently demonstrate a dysregulation of tumor cell glycolysis, chemotaxis, and IFNGR1 expression by the RAC1A159V mutation." (PMID 41160695, 2025). "We investigated the prevalence of those mutations before ICB by collating data from The Cancer Genome Atlas (TCGA) for pre-treatment tumours which harboured mutations in the IFNγ receptor subunits (IFNGR1/2) or downstream signalling molecules (JAK1/2, STAT1)." (PMID 39746898, 2025). "We found that loss of IFNγR1 on tumour cells results in intra-tumoural IFNγ accumulation, which induces pro-inflammatory signalling of immune-infiltrating populations." (PMID 39746898, 2025). "PECAM1 expression was also closely associated with ETS1/PLAT and CD274 (PDL1)/IFNGR1, indicating close involvement of tumor angiogenesis with unique proteolysis and tumor immunity." (PMID 38557819, 2024). "After two days of co-culture with EGFR CAR T cells, resistant clones of tumor cells were enriched for loss of genes involved in IFNγ-mediated signaling, such as IFNGR1 and JAK1." (PMID 36189315, 2022). "The tumor-specific component of the ICI resistance was due to genetic loss of IFNGR1/2 and JAK2, and amplification of IFN signaling inhibitors SOCS1 and PIAS4." (PMID 35269844, 2022). "To this end, we employed IFNGR1−/− mice and adoptive transfer of total IFNGR1−/− T cells to tumor-bearing mice, and found that loss of IFNGR1 in T cells completely abrogated the efficaciousness of combined anti-CTLA-4 and anti-PD-1 therapy." (PMID 34830176, 2021). "To determine the role of both helper and cytotoxic activities of Trp1 cells in tumor rejection, we transferred either Trp1 or perforin-1-deficient Trp1 cells (Prf1−/−Trp1) into wild-type (WT) or Ifngr1−/− hosts combined with radiation and αCTLA-4." (PMID 31924474, 2020). "Tumor-associated macrophages were more abundant and were more favored toward M2 polarization in Ifngr1−/−ApcMin/+ mice than in Ifngr1+/+ApcMin/+ mice." (PMID 27286456, 2016). "To address this, we challenged WT or Ifngr1−/− mice, which are deficient of IFN-γR1 (the essential receptor for IFN-γ) with MB49 tumour cells, followed by combination treatment." (PMID 27498556, 2016). "Modulating IFNGR1 palmitoylation levels in tumour tissues may reduce "adaptive resistance" caused by OSCC-derived extracellular vesicles deliver IFNGR1." (PMID 40657375, 2025). "At baseline, mdTAM_4 was particularly high in Ifngr1 expression, despite low expression of genes associated with IFNγ stimulation, potentially indicating an unutilised capacity to respond to type-II interferon that is held in check by the tumour environment." (PMID 40523200, 2025). "Together, these findings provide strong evidence for the tumor-intrinsic molecular alterations induced by the RAC1A159V mutation that promote tumor cell glycolysis, suppress chemokine production, and reduce cell surface IFNGR1 via glycosphingolipid mediated mTOR activation." (PMID 41160695, 2025). "Indeed, loss of the receptor for IFNγ (IFNGR1) in tumor cells abrogated DuoBody-CD3x5T4–induced tumor cell kill." (PMID 36271507, 2022). "The deficiency of IFNGR1 causes tumor cells to be unresponsive to IFNγ and promotes tumor growth." (PMID 35127816, 2021). "In this study, we assessed whether a loss-of-function mutation of the interferon (IFN)-γ receptor 1 (IFNGR1) in tumor cells can interfere with anti-PD-L1 therapy." (PMID 32155707, 2020). "We next examined tumor-associated macrophages (TAMs) in intestinal polyps by immunohistochemical staining of F4/80, a marker for macrophages, and found that macrophages were more abundantly infiltrated in tumors of Ifngr1−/−ApcMin/+ mice than in those of Ifngr1+/+ApcMin/+ mice." (PMID 27286456, 2016). "We also noted that RMC tumor cells treated with ICT overexpress IFNGR1 and that genetic knockout of IFNGR1 prevented hyperprogression and sensitized tumors to ICT in pre-clinical settings." (PMID 41290625, 2025).
tumor (continued). "Consistent with the in vitro data, mTOR downstream p4E-BP1 was up-regulated, and cell surface IFNGR1 was down-regulated in CT26 RAC1A159V/WT tumor cells in vivo." (PMID 41160695, 2025). "The up-regulation of Ifngr1 expression in Il1r2−/− iCAF can potentially help enhance the response to interferon-gamma and promote anti-tumor immunity." (PMID 40767963, 2025). "The IFN-γ–IFNGR1/2–JAK1/2–STAT1–IRF1 axis is central to anti-tumor immunity, and dysregulation of this pathway can perturb PD-L1 levels and alter sensitivity to immunotherapy." (PMID 41463246, 2025). "IFNGR1 demonstrated significant variability across multiple parameters, including tissue type, tumor stage, sex, and histological subtype, highlighting its potential clinical relevance in PAAD." (PMID 41209574, 2025). "Mechanistically, RAC1A159V up-regulates glycosphingolipid biosynthesis to activate mTORC1 signaling in tumor cells, which in turn increases glycolysis, impairs key chemokine production, and decreases IFNGR1 expression of the tumor cells." (PMID 41160695, 2025). "These in vivo data further support a mechanism by which hyperactive mTORC1 signaling in RAC1A159V tumors attenuates ICI efficacy through increased tumor glycolysis, suppressed chemokine production, and down-regulated IFNGR1 expression." (PMID 41160695, 2025). "In line with in vitro cell culture observations, rapamycin treatment promoted chemokine production and IFNGR1 expression within tumor cells, suggesting a restoration of immune cell infiltration and tumor response to IFN-γ signaling (6 J & S13E)." (PMID 41160695, 2025). "The heterodimeric IFNGR1/IFNGR2 receptor complex on tumor cells binds to IFN-γ released by tumor-specific T lymphocytes, activating JAK1 and JAK2, which subsequently phosphorylate a transcription factor known as STAT1." (PMID 38785789, 2024). "VC treatment enhanced IFN-γ expression in T cells and IFNGR1 in tumor cells, which was dependent on the expression of TET2 in tumors." (PMID 39388288, 2024). "The results showed that deletion of IFNγR1 in glioblastoma cells reduced the overall binding affinity of tumor cells to CAR-T cells." (PMID 38115906, 2023). "Activated IFNGR1 stimulates the recruitment of immune suppressive neutrophils to the tumor site, facilitating tumor growth and metastasis formation in patients with triple negative breast cancer (TNBC)." (PMID 35346215, 2022). "IFN-γ induced tumor dormancy when the interferon-gamma receptor 1 (IFNGR1) expression level was low but resulted in tumor elimination when it was high." (PMID 36612080, 2022). "We attributed these observations to the physiological role of STUB1 to downregulate the level of IFNGR1 on tumour cells’ surface, thereby reducing their ability to sense IFNγ—a key cytokine secreted by activated T cells and NK cells." (PMID 35982220, 2022). "Expression levels of the tumor cell–autonomous gene IFNGR1 and downstream signaling axis and effector genes, including JAK1, JAK2, and IRF1, were all significantly lower in PRC2-loss tumors than in PRC2-wt tumors (P < 0.05)." (PMID 35852856, 2022). "The depletion of the IFNGR1 gene in B16 tumor cells suppressed IFN-γ mediated apoptosis and decreased the antitumor effects of anti-CTLA-4 therapy in a mouse model." (PMID 36189283, 2022). "In tumor samples, LINC01198’s expression level was positively associated with IFNGR1 expression and IFN-γ signature." (PMID 36475797, 2022). "Preclinical studies have shown that defects in IFNGR1 (IFN-γ receptors) and JAK1/2 genes cause tumor cells to be unresponsive to IFN- γ, which allows tumor cells to grow in the presence of IFN- γ." (PMID 35740594, 2022). "Parental and 5T4, 5T4/Fas, or 5T4/IFNGR1 double-KO MDA-MB-231 tumor cells were mixed in different ratios and cocultured with purified T cells and DuoBody-CD3x5T4." (PMID 36271507, 2022).